MSRB2 (methionine sulfoxide reductase B2)
Description:
Methionine-sulfoxide reductase that specifically reduces methionine (R)-sulfoxide back to methionine. While in many cases, methionine oxidation is the result of random oxidation following oxidative stress, methionine oxidation is also a post-translational modification that takes place on specific residue. Upon oxidative stress, may play a role in the preservation of mitochondrial integrity by decreasing the intracellular reactive oxygen species build-up through its scavenging role, hence contributing to cell survival and protein maintenance.
Synonyms: CBS-1; MSRB; CGI-131; PILB; CBS1
Tractability: PROTAC: its protein half-life has been measured.
Target class: Enzyme; Oxidoreductase
Gene: Protein-coding gene on chromosome 10 (23,095,579 to 23,122,013, forward strand). Ensembl gene ENSG00000148450.
Subcellular location: Mitochondrion
Pathways (Reactome):
Metabolism of proteins: Protein repair
Gene Ontology:
Molecular function: protein binding; actin binding; peptide-methionine (R)-S-oxide reductase activity; zinc ion binding; L-methionine (R)-S-oxide reductase activity; oxidoreductase activity, acting on a sulfur group of donors, disulfide as acceptor
Biological process: actin filament polymerization; protein repair; response to oxidative stress
Cellular component: mitochondrion; cytosol; cytoplasm
Genetic constraint (gnomAD): Loss-of-function variants: 18 observed, 17.72 expected, observed/expected ratio (o/e) 1.02, 90% interval 0.7 to 1.5. The upper end of that interval is the gene's LOEUF score, 1.5, which puts it in group 6 of 6, group 1 being the genes least tolerant of losing a copy. Missense variants: 190 observed, 200.33 expected, observed/expected ratio (o/e) 0.95, 90% interval 0.84 to 1.07. Synonymous variants: 96 observed, 83.99 expected, observed/expected ratio (o/e) 1.14, 90% interval 0.97 to 1.35.
Homologues: Orthologues: chimpanzee MSRB2 (99% identical), macaque MSRB2 (97% identical), dog MSRB2 (84% identical), guinea pig MSRB2 (75% identical), mouse Msrb2 (75% identical), pig MSRB2 (63% identical), rat Msrb2 (63% identical), Caenorhabditis elegans msra-1 (8% identical), Drosophila melanogaster MsrA (8% identical). Paralogues in human: MSRB3 (38% identical), MSRB1 (21% identical), MSRA (16% identical).
Diseases named in the same sentence as MSRB2 in open-access papers:
MSRB2 is named in the same sentence as 29 diseases in open-access papers, as found by Europe PMC text mining. Sharing a sentence is not in itself a finding about the gene and the disease. The quoted sentences say what the papers report.
Parkinson disease (6 papers, 2019 to 2024). A progressive degenerative disorder of the central nervous system characterized by loss of dopamine producing neurons in the substantia nigra and the presence of Lewy bodies in the substantia nigra and locus coeruleus. "As we have highlighted, mutation of Met192 (M192L and M192V) is recognized to be associated with Parkinson's disease, the same site as the MetO, and its reduction by MsrB2." (PMID 31282614, 2019). "Pathophysiological importance is highlighted in human subjects, where increased MsrB2 expression in diabetes mellitus leads to increased platelet mitophagy, and in platelets from Parkinson's disease patients, where reduced MsrB2 expression is associated with reduced mitophagy." (PMID 31282614, 2019). "Intriguingly the authors also present data suggesting that this pathway is dysfunctional in platelets from patients with Parkinson's disease (PD) and demonstrate selective reduction in MsrB2 and LCII, and increased apoptosis in PD platelets." (PMID 31313883, 2019). "Based on these observations, we recruited consecutive consenting patients from the Parkinson's disease clinic at Yale to assess for MsrB2/mitophagy and platelet apoptosis." (PMID 31282614, 2019). "Enhancing MsrB2 may be a novel treatment strategy for oxidative diseases such as DM and for Parkinson's disease." (PMID 31282614, 2019). "Based upon our human patient studies, this Parkin/MsrB2/LC3 protein complex may be an important principle for Parkin‐dependent mitophagy in DM and other disease processes such as Parkinson's disease." (PMID 31282614, 2019).
diabetes (3 papers, 2019 to 2026). "In a chronic, bodily disease such as diabetes, a global knockout better reflects the natural effects of a germline mutation or variant in the MsrB2 gene that a patient might experience." (PMID 38970135, 2024). "There is increased MsrB2 expression observed in diabetes, and its decrease can induce more heart complications than WT DM." (PMID 38970135, 2024). "The characteristics of DM observed in MsrB2 KO DM mice are similar to those observed in lean diabetes, which is prevalent in the Asian population." (PMID 38970135, 2024). "Thus, the autophagic/mitophagy process activated by MsrB2 may be cytoprotective during diabetes." (PMID 38970135, 2024). "However, the function of MsrB2 in other tissues in the context of diabetes is unknown." (PMID 38970135, 2024). "Our results suggest that both WT DM and MsrB2 KO DM mice display similar patterns, indicating that MsrB2 is not a direct regulator of diabetes." (PMID 38970135, 2024). "In non-obese diabetes, the concomitant reduction of MsrB2 expression may further accelerate hypertensive remodeling, highlighting a mechanism that could explain the higher incidence of cardiovascular complications observed in non-obese diabetic individuals." (PMID 41907527, 2026).
diabetic cardiomyopathy (1 paper, 2024). Diabetic cardiomyopathy is a disorder of the heart muscle in people with diabetes. "Our study demonstrates that increased MsrB2 expression in the heart protects against diabetic cardiomyopathy." (PMID 38970135, 2024). "Methionine sulfoxide reductase B2 (MsrB2) can reverse oxidation induced MetO in mitochondrial proteins, so we investigated its role in diabetic cardiomyopathy." (PMID 38970135, 2024).
endothelial dysfunction (1 paper, 2019). In vascular diseases, endothelial dysfunction is a systemic pathological state of the endothelium (the inner lining of blood vessels) and can be broadly defined as an imbalance between vasodilating and vasoconstricting substances produced by (or acting on) the endothelium. "Although these results support a role for MsrB2 in mitophagy, endothelial dysfunction (arising from MsrB2 knockout) may also lead to platelet apoptosis, and thus, we needed a platelet‐selective knockout." (PMID 31282614, 2019).
fibrosis (1 paper, 2024). the formation of excess fibrous connective tissue in an organ or tissue in a reparative or reactive process. "In addition, MsrB2 KO DM mice demonstrated lipid accumulation, cardiac fibrosis, hemorrhage, abnormalities in cardiac tissue, and electrophysiological dysfunctions compared to WT DM mice." (PMID 38970135, 2024). "Notably, despite the similar glucose tolerance of WT DM and MsrB2 KO DM mice, mitochondrial dysfunction, cardiac fibrosis, myocardial tissue abnormalities, and decreased body weight were observed in MsrB2 KO DM mice." (PMID 38970135, 2024).
glioma (1 paper, 2023). A benign or malignant brain and spinal cord tumor that arises from glial cells (astrocytes, oligodendrocytes, ependymal cells). "The expression levels of risk factors IL4I1, SMS, and ADI1 in high-grade gliomas were higher than those in lower‐grade gliomas, while the protein expression levels of protective factor GCLC, MSRB2, MTAP and MPST were exactly the opposite." (PMID 38057821, 2023).
hearing loss (1 paper, 2025). "Among the four paralogs (MSRA, MSRB1, MSRB2, MSRB3), so far, only MSRA and MSRB3 have been associated with hearing loss." (PMID 40827380, 2025).
ischemia (1 paper, 2023). A hypoperfusion of the BLOOD through an organ or tissue caused by a PATHOLOGIC CONSTRICTION or obstruction of its BLOOD VESSELS, or an absence of BLOOD CIRCULATION. "A recent study has found that betaine could increase the expression of MetO reductases b1 (Msrb1) and b2 (Msrb2) to exert a neuroprotective effect in ischemia/reperfusion injury‐induced brain damage." (PMID 37183324, 2023).
myocardial hypertrophy (1 paper, 2024). "Additionally, ET-1 (a myocardial hypertrophy inducer) induced ROS and increased autophagy and MsrB2 expression in H9C2 cells." (PMID 38970135, 2024).
infection (14 papers, 2011 to 2026). The state of being infected such as from the introduction of a foreign agent such as serum, vaccine, antigenic substance or organism. "This study also showed that pepper lines silenced for MSRB2 expression exhibit increased ROS production, accelerated cell-death in the case of incompatible infection by a bacterial Xanthomonas race and increased susceptibility following infection by a virulent strain." (PMID 30158486, 2018).
cardiovascular disease (1 paper, 2024). "However, further studies are needed to validate these findings and explore the potential clinical applications of MsrB2 inducers in managing cardiovascular disease in DM patients." (PMID 38970135, 2024).
heart disease (1 paper, 2024). "Additionally, the use of MsrB2 analogs or inducers may be a potential therapeutic strategy for managing DM heart disease." (PMID 38970135, 2024).
neurodegenerative disease (1 paper, 2019). A disorder of the central nervous system characterized by gradual and progressive loss of neural tissue and neurologic function. "This provides possible mechanistic insights linking MsrB2 to the development of neurodegenerative diseases." (PMID 31282614, 2019).
MSRB2 also shares sentences with these, for which no sentence is quoted: cancer (2 papers); Alzheimer disease (1); bacteremia (1); complication (1); endocarditis (1); focal segmental glomerulosclerosis (1); gastrointestinal tract infections (1); heart failure (1); Hypertension (1); meningitis (1); Myocardial fibrosis (1); Parkinson's (1); peritonitis (1); Sepsis (1); viral infections (1); vitiligo (1).